ACACB (acetyl-CoA carboxylase beta)
Diseases named in the same sentence as ACACB in open-access papers (continued):
Sharing a sentence is not in itself a finding about the gene and the disease.
motor neuron degeneration (1 paper, 2025). "In ALS, ACACB (Importance 27.3), a fatty acid synthesis enzyme, interacted with Biotin (PUBCHEM_CID: 171548), indicating metabolic interventions for motor neuron degeneration." (PMID 40864790, 2025).
oral cancer (1 paper, 2022). "The expression levels of FABP3, PPARG, PLIN5, ACACB, and PDK4 in oral cancer samples were significantly lower than those in adjacent normal samples (all p < 0.05) and then were included in the prognosis analysis." (PMID 36478991, 2022).
osteoarthritis (1 paper, 2026). A noninflammatory degenerative joint disease occurring chiefly in older persons, characterized by degeneration of the articular cartilage, hypertrophy of bone at the margins and changes in the synovial membrane. "The temporal analysis of gene expression patterns in GSE89408 RNA-seq validation dataset was conducted for the gene expression levels of PDK1, XBP1 and ACACB across different disease stages, including normal, arthralgia, osteoarthritis, undifferentiated arthritis, RA (early), and RA (established)." (PMID 41583523, 2026).
papillary thyroid carcinoma (1 paper, 2022). "ACACB may be a new treatment strategy for overcoming resistance to BRFRV600E inhibitors in papillary thyroid carcinoma." (PMID 36111743, 2022).
rectal cancer (1 paper, 2022). A primary or metastatic malignant neoplasm that affects the rectum. "The pancancer analysis in TCGA datasets indicated lower expression of ACACB in tumor tissue, including colon and rectal cancers." (PMID 36111743, 2022).
schizophrenia (1 paper, 2024). A major psychotic disorder characterized by abnormalities in the perception or expression of reality. "In fatty acid synthesis, DECR1 was upregulated in schizophrenia but downregulated in ketosis, whereas ACACB and HADH were upregulated in both." (PMID 39125835, 2024).
steatosis (1 paper, 2020). Increased lipid within the cytoplasm of cells. "In our experiments, LPS alone did not affect the levels of ACACA, ACACB nor FASN in HepG2 cells, indicating that it does not induce DNL-mediated steatosis in HCC cell model either." (PMID 32284043, 2020).
cancer (23 papers, 2018 to 2026). A tumor composed of atypical neoplastic, often pleomorphic cells that invade other tissues. "It has been reported that aberrant expression of ACACB increases the risk in different cancer types." (PMID 34258555, 2021). "Apart from being known to be actively involved in the body's fatty acid synthesis, aberrant expression of the ACACB genes could also raise the risk for cancer." (PMID 40842862, 2025). "Mitochondrial proteins OSBPL1A and ACACB can enhance radiosensitivity, reduce drug resistance, and offer new hope for treating recurrent cancer." (PMID 40290445, 2025). "Subsequently, potential cancer-associated miRNA clusters upstream of ANGPTL1, SOCS3, ACACB, and EHHADH were predicted via integrated cross-analysis using multi-databases, including miRDB, TargetScan, RNAInter, and miRWalk." (PMID 40426998, 2025). "i.e., ACACB and RXRG were with high mutation frequency and down-expressed in most cancer types, including UCEC, LUAD, LUSC, COAD, BLCA and HNSC." (PMID 31074374, 2019). "ACACB promotes lipogenesis, supporting rapid cancer cell proliferation." (PMID 40426878, 2025). "In addition, based on the CCLE database, ACACB is expressed in almost all cancer cell lines, including CRC cell lines." (PMID 36111743, 2022). "The negatively correlated genes were enriched in “calcium signaling pathway,” “PPAR signaling pathway,” and “proteoglycans in cancer”, and ACACB, PPARG, CAV1 may be the core of these genes." (PMID 34257557, 2021). "We first confirmed the targeting effect of miR-452-3p and miR-589-3p on ACACB and EHHADH in cancer cell lines using miRNA inhibitors." (PMID 40426998, 2025). "Impressively, TK1, RRM2 and IMPDH1 were positively correlated with Myc/Myc signatures in multiple cancer types, whereas HSD17B6, PYGM and ACACB were negatively correlated with Myc/Myc signatures." (PMID 36629054, 2023). "EPHX2, ACSF2, CYP27A1, ACSS1, and ALDH1L1 showed hypermethylation in several types of human cancer; on the contrary, AKR1B10, POLG2, NDUFB8, ACACB, and MRPS22 consistently showed hypomethylation in several types of human cancer." (PMID 37223030, 2023). "Because CPT1 is a rate-limiting enzyme of FAO responsible for acyl-carnitine transport into the mitochondria, ACC2 (acetyl-coA carboxylase beta, ACACB) activity and abundance are tightly controlled in many tissues, including cancer cells." (PMID 32487689, 2020). "However, the data from different cancer centers by the Oncomine tool showed opposite results between CRC tissue and normal colon tissue, showing decreased ACACB expression in tumor tissues." (PMID 36111743, 2022). "Although the role of ACACB in HCC was still not reported, previous studies indicated that ACACB played an important role in the initiation and progression of other cancers." (PMID 30341252, 2018).
tumor (18 papers, 2019 to 2026). "Previous analysis demonstrated that ACACB (acetyl-CoA carboxylase beta) was downregulated in BC and positively associated with survival time, which may be a potential target to reduce drug resistance in tumor cells." (PMID 37893423, 2023). "In Li’s study, ACACB was found to be highly expressed in laryngocarcinoma and even related to tumor stage and degree of laryngocarcinoma cell differentiation." (PMID 36111743, 2022). "Previous studies establishing the importance of de novo lipogenesis in tumor progression and the knockout of ACACB genes in mice indicated a crucial role of ACACB in liver carcinogenesis." (PMID 36478991, 2022). "Network topology and machine learning approaches consistently highlighted ACACB, ADH4, and PCK1 as core hub genes, all of which showed significant differential expression between tumor and normal tissues and demonstrated strong diagnostic performance (AUC > 0.87)." (PMID 42032347, 2026). "The ACC family influences tumor progression, with ACACB being an important member of this family." (PMID 40084144, 2025). "ACACB expression was high in tumor tissues, and different expression levels of ACACB could be found in different tumor cell lines." (PMID 36111743, 2022). "Moreover, Valvoet al. demonstrated that BRAFV600E can downregulate ACACB level and sh-ACACB could increase tumor growth and vemurafenib resistance." (PMID 36111743, 2022). "The inhibition of fatty acid oxidation through ACACB could perturb tumor cells absorbing energy." (PMID 34322485, 2021). "Compared to adjacent normal tissues, tumor tissues exhibited significantly reduced expression of PTGIS, DGKB, HSD17B13, INMT, and ACACB, while PLA2G10, GRHL1, LIPG, and PLA2G4F were markedly upregulated." (PMID 40426878, 2025). "Significant SNV alterations were observed in BRCA2, ACACB, BRCA1, MSH6 and IFI16 in most tumour types." (PMID 37660060, 2023). "The hot genes with the most positive signal events in the normal-specific group were RBPJ, PFKFB3, CAMK1D, ACACB, and WWOX, whereas the hot genes in the tumor-specific group were SLC35F3, PCDH7, NF1, and RAB27B." (PMID 36895481, 2023). "Substantial CNV deletions were observed in PABPC5, MSH6, IFI16, GNS, ERCC4, BRCA1 and ACACB, while substantial CNV amplification was observed in most tumour types for the remaining genes." (PMID 37660060, 2023). "The results showed that the expression of ACACB, ATP8B4, C14orf28, CIRBP, and DTWD1 were higher in normal tissues, and the content of CDC6, DSP, HMGB3, HNRNPA3P1, PPP1R14C, and TPX2 were higher in tumor tissues." (PMID 35778922, 2022). "Based on metabolic modeling analysis, we identified four target genes, namely SOAT1, CRLS1, ACACB, and GPD2, whose inhibition can block the growth of ccRCC tumor cells with relatively low toxicity to normal tissue cells." (PMID 34258555, 2021). "ACACB, ADH1B, and SCD, as key genes related to FAM, play important roles in tumor progression in PTC and may serve as potential therapeutic targets in PTC patients." (PMID 40084144, 2025). "Similarly, genes such as CAV1, ACACB, NTRK2, KLF4, and MYH11 were the key down-regulated hub genes suggesting a possible role of their decreased expression in breast carcinogenesis." (PMID 31292488, 2019).
infection (3 papers, 2009 to 2024). The state of being infected such as from the introduction of a foreign agent such as serum, vaccine, antigenic substance or organism. "Ketogenesis was likely higher in LCMV-WE infected rhesus macaques than in the mildly-infected macaques since fatty acid synthesis via acetyl-coenzyme A carboxylase beta (ACACB) was more down-regulated in the virulent infection." (PMID 19216742, 2009).
ACACB also shares sentences with these, for which no sentence is quoted: ovarian carcinoma (3 papers); colorectal cancer (2); leukemia (2); metabolic disease (2); type 1 diabetes (2); Alzheimer disease (1); atherosclerosis (1); breast (1); cardiac hypertrophy (1); cardiomyopathy (1); cervical cancer (1); diabetic retinopathy (1); Hyperglycemia (1); hyperuricemia (1); Hypocholesterolemia (1); laryngeal carcinoma (1); laryngeal squamous cell carcinoma (1); lipidemia (1); lung carcinoma (1); lymph node metastasis (1); metabolic energy disorders (1); nasopharyngeal carcinoma (1); non-alcoholic fatty liver disease (1); nonalcoholic steatohepatitis (1); osteosarcoma (1); pancreatic cancer (1); Proteinuria (1); squamous cell carcinoma (1); type 2 diabetic nephropathy (1).